SIRT6 (sirtuin 6)
Diseases named in the same sentence as SIRT6 in open-access papers (continued):
Sharing a sentence is not in itself a finding about the gene and the disease.
endothelial dysfunction (continued). "The increased SIRT6 expression following high-glucose exposure might be a compensatory response to hyperglycemia-induced damage, since SIRT6 is involved in the DNA-damage repair system and protects against endothelial dysfunction and vascular inflammation." (PMID 35562979, 2022). "As such, activating SIRT6 may be beneficial in endothelial dysfunction-related inflammation diseases." (PMID 35528512, 2022). "Moreover, endothelial cell-specific deletion of Sirt6 dampened endothelial-dependent relaxation of blood vessel in mice, suggesting a role of Sirt6 in endothelial dysfunction." (PMID 34712151, 2021). "In SIRT6 knockout mice, atherosclerotic plaque was enlarged, plaque vulnerability was enhanced, and the expression of ICAM-1 in aortic endothelial cells was significantly up-regulated, implying that SIRT6 is the primary negative regulator of endothelial dysfunction and atherosclerotic development." (PMID 33855020, 2021). "SIRT6 protects endothelial cells from telomere and DNA damage, prevents premature senility, and maintains the ability of cell replication and angiogenesis in vitro, all of which are known to inhibit the development of endothelial dysfunction." (PMID 33855020, 2021). "Loss of SIRT6 is known to associate with vascular endothelial dysfunction, senescence, and inflammation, whereas induction of SIRT6 expression by exogenous vector-driven SIRT6, antioxidant, and anti-inflammatory signals prevents or ameliorates endothelial dysfunction, senescence, and inflammation." (PMID 33171439, 2020). "This led to the hypothesis that SIRT6 may also play an important role in infection induced endothelial dysfunction." (PMID 23132960, 2012). "Thus, our objective was to test the hypothesis that reductions in SIRT6 elicit endothelial dysfunction in young, genetically altered mice." (PMID 34744793, 2021). "The Sirt6 mRNA-carrying EMPs may ameliorate endothelial dysfunction in diabetic patients." (PMID 29371988, 2017). "In addition, SIRT6 expression is decreased in endothelial cells (ECs) under chronic stimulation with lipopolysaccharide (LPS), hydrogen peroxide (H2O2) and high glucose, three of which are risk factors associated with endothelial dysfunction and atherogenesis." (PMID 27249230, 2016). "It is clear that the downregulation of SIRT6 reduces GATA5 expression, and this leads to endothelial dysfunction through reduced nitric oxide bioavailability, increased permeability, and subsequent hypertension and cardiorenal injury." (PMID 40218970, 2025). "We found that SIRT6 inhibited HIF1α transcriptional activity by antagonizing p300 acetylation of H3K9 at the Ero1α promoter, thereby suppressing Ero1α expression and augmentation of ERS‐induced endothelial dysfunction." (PMID 37598403, 2023). "Because FOXO1 contributes to endothelial dysfunction and has been shown to directly bind to the ICAM-1 promoter and activate ICAM-1 transcription, it is plausible to speculate that SIRT6 might modulate oxLDL-induced ICAM-1 expression by targeting FOXO1." (PMID 35246513, 2022). "First, while we have identified activation of NADPH oxidase as a potential mechanism contributing to endothelial dysfunction in this model, we did not identify the specific mechanistic steps whereby SIRT6 induces this phenomenon." (PMID 34744793, 2021). "In HUVECs, SIRT6 significantly promotes eNOS activity and down-regulates the expression of intercellular adhesion molecules (ICAM-1) and VCAM1 by activating Nrf2, thereby alleviating endothelial dysfunction induced by CCs." (PMID 33855020, 2021). "To further investigate whether SIRT6 haploin-sufficiency aggravates endothelial dysfunction under HFD feeding conditions, we challenged SIRT6+/− mice and WT mice with a HFD for 3 months." (PMID 27249230, 2016).
endothelial dysfunction (continued). "Additionally, Ero1α silencing could restore the protein levels of VE‐cadherin, p‐eNOS and eNOS in SIRT6‐deficient HUVECs under OGD/R conditions, which suggested that inhibiting Ero1α could substantially ameliorate OGD/R‐induced endothelial dysfunction in the absence of SIRT6." (PMID 37598403, 2023).
Hepatic steatosis (27 papers, 2011 to 2025). Steatosis is a term used to denote lipid accumulation within hepatocytes. "SIRT6 also regulates the deacetylation of various glycolipid metabolism‐related genes, with SIRT6‐deficient mice showing upregulation of triglyceride synthesis genes, contributing to fatty liver disease development." (PMID 40060193, 2025). "Given that FoxA1 repressed lipid droplet formation via enhancing Sirt6 expression in hepatocytes, we further examined the involvement of Sirt6 in FoxA1 deficiency-mediated hepatic steatosis in mice." (PMID 39277582, 2024). "Sirt6 suppresses Serpina12 in the liver and its deficiency contributes to the onset of liver steatosis and spontaneous tumor development." (PMID 38332150, 2024). "In the present study, we have identified a novel target, Serpina12, that is suppressed by Sirt6 in the liver and contributing to the onset of liver steatosis when Sirt6 is deficient." (PMID 38332150, 2024). "Hepatic ablation of SIRT6 results in fatty liver disease, yet the potential mechanism of SIRT6 deficiency, particularly in relation to downstream mediators for NAFLD, remains elusive." (PMID 38332150, 2024). "Hepatic SIRT6 deficiency leads to fatty liver in mice, and the expression of SIRT6 is reduced in human NAFLD samples." (PMID 36880305, 2023). "Hepatic deficiency of Sirt6 in mice has been shown to cause hepatic steatosis, inflammation, and fibrosis, hallmarks of alcoholic and nonalcoholic steatohepatitis." (PMID 36831330, 2023). "As SIRT6 has been implicated in multiple diseases including fatty liver disease and liver cancer, a number of chemical modulators (activators or inhibitors) targeting SIRT6 have been developed." (PMID 36831330, 2023). "Liver-specific Sirt6 knockout (LKO) mice are more susceptible to Western diet-induced fatty liver disease, manifesting elevated serum and hepatic diacylglycerol and triglyceride levels compared to WT mice." (PMID 36831330, 2023). "We aim to investigate the underlying mechanisms and pharmacological interventions of SIRT6 on hepatic steatosis treatment." (PMID 36558977, 2022). "In a recent study, it was confirmed that the deacetylation of the X-box binding protein 1 (XBP1s) by SIRT6 can alleviate hepatic steatosis caused by endoplasmic reticulum stress." (PMID 33274005, 2020). "Sirt6 regulates the hepatic accumulation of triglycerides (TG), which is associated with fatty liver disease." (PMID 29535637, 2018). "Sirt6 has been implicated in the regulation of hepatic lipid metabolism and the development of hepatic steatosis." (PMID 21373642, 2011). "Fatty liver diseases have been implicated in liver cancer formation, therefore, we would like to investigate whether Sirt6 deficiency could trigger the onset of liver cancer in advanced stages and elucidate the underlying mechanism for cancer formation." (PMID 38332150, 2024). "Importantly, CRISPR-Cas9 mediated Serpina12 knockout in the liver ameliorated fatty liver disease caused by Sirt6 ablation." (PMID 38332150, 2024). "Additionally, we demonstrated that Sirt6 overexpression or pharmacological activation counteracted Tm-induced ER stress to alleviate hepatic steatosis and associated pathologies." (PMID 31541078, 2019). "Human fatty liver samples exhibited significantly lower levels of SIRT6 than normal controls and liver-specific deletion of Sirt6 in mice causes increased glycolysis, triglyceride synthesis, reduced β-oxidation, and leads to liver steatosis." (PMID 30574122, 2018). "Additionally, loss of SIRT6 induced hepatic steatosis through the deacetylation of X-box-binding protein 1 (XBP1s), a key modulator of ER stress, while SIRT6 overexpression prevented ER stress activation triggered by tunicamycin, a well-known ER stress inducer." (PMID 35743232, 2022).
Hepatic steatosis (continued). "In this study, we aimed to determine whether deletion, overexpression, or pharmacological activation of Sirt6 alters ER stress-induced hepatic steatosis and the associated pathology and to investigate the molecular mechanism of Sirt6 regulation of the UPR elicited by ER stress." (PMID 31541078, 2019). "As determined by HE staining, liver steatosis was promoted by FoxA1 knockout, which was abrogated when Sirt6 was overexpressed at different stages of NAFLD (4, 8, 12 weeks)." (PMID 39277582, 2024). "The removal of ubiquitin modification from SIRT6 by ubiquitin-specific peptidase (USP10) can stabilize SIRT6 and protect against diet-induced hepatic steatosis." (PMID 36831330, 2023). "When Sirt6 is deleted in the mouse liver, the knockout mice develop hepatic steatosis on both normal chow and high-fat diets." (PMID 36831330, 2023). "SIRT6 knockout or hepatic SIRT6 knockout in C57 mice largely abolished the effect of ATL I on ameliorating hepatic steatosis." (PMID 36558977, 2022). "In the NFALD model, USP10 regulates hepatic steatosis by interacting with SIRT6 and inhibiting its ubiquitination and degradation." (PMID 33133065, 2020). "Here, we demonstrate that XBP1s is a deacetylation target of Sirt6 and that its deacetylation protects against ER stress-induced hepatic steatosis." (PMID 31541078, 2019). "Second, Tm-stimulated hepatic steatosis was increased in Sirt6 KO mice but decreased by Sirt6 augmentation, which was assessed by perilipin immunostaining and the TG content of the liver." (PMID 31541078, 2019). "To investigate the direct role of Sirt6 during the development of ER stress-induced hepatic steatosis, we compared the response of WT and KO mice to a Tm challenge." (PMID 31541078, 2019). "Specifically, the abundance of acetylated XBP1s and concordant hepatic steatosis were increased in hepatocyte-specific Sirt6 knockout and obese mice but were decreased by genetic overexpression and pharmacological activation of Sirt6." (PMID 31541078, 2019). "Recent studies indicated that the PPARγ activation showed a protective effect by increasing SIRT6 expression in animal models of hepatic steatosis and Huntington’s disease (HD)." (PMID 30791908, 2019). "To identify the UPR transducers responsible for hepatic steatosis in Sirt6 KO mice, we carefully investigated the activation status of three transducers of ER stress signaling." (PMID 31541078, 2019). "Damage in terms of specificity formation to the SIRT6 gene of mice liver can induce fatty liver because of the enhanced glycolysis and the synthesis of triglycerides." (PMID 26057744, 2015). "Our previous reports regarding RGZ and hepatic steatosis demonstrated that RGZ-mediated improvement of hepatic steatosis is by activating the Sirt6-AMPK pathway in rats and in AML12 mouse hepatocytes." (PMID 25133775, 2014). "The involvement of Sirt1/6 in the RGZ-mediated effect against hepatic steatosis was evaluated by single or double knockdown of Sirt1 and Sirt6 in a hepatocyte steatosis model." (PMID 25133775, 2014). "In previous reports from our group, the protective action of RGZ against hepatic steatosis is by coordinated regulation of adiponectin, Sirt6, and AMPK." (PMID 25133775, 2014). "In this paper, we have demonstrated that RGZ improved hepatic steatosis, accompanied by an elevation in adiponectin, Sirt6 and its related targets, as well as AMPK phosphorylation, both in vivo and in vitro." (PMID 21373642, 2011). "The aim of this study was to address the potential role of Sirt6 in the protective effects of rosiglitazone (RGZ) on hepatic steatosis." (PMID 21373642, 2011). "Collectively, these data demonstrate that attenuation of hepatic steatosis by RGZ is likely mediated by the activation of the Sirt6-AMPK pathway, suggesting Sirt6 as a therapeutic target for hepatic steatosis and its related diseases." (PMID 21373642, 2011).
Hepatic steatosis (continued). "Overexpression of Sirt1 and Sirt6 was recently reported to improve glucose control, hepatic steatosis and inflammation." (PMID 21373642, 2011). "Taken together, these findings support the improvement of hepatic steatosis by RGZ by activation of the Sirt6-AMPK pathway, and suggest Sirt6 as a therapeutic target for hepatic steatosis." (PMID 21373642, 2011). "Our study is the first to demonstrate the involvement and importance of Sirt6 in RGZ-mediated protection against hepatic steatosis." (PMID 21373642, 2011). "Liver FoxA1 knockout mice developed severe liver steatosis, which could be ameliorated by sirtuin 6 (Sirt6) overexpression." (PMID 39277582, 2024). "Thus, HFD-induced deSUMOylation of FoxA1 led to hepatic steatosis via inactivation of Sirt6/Pparα pathway." (PMID 39277582, 2024). "Sirt6-LKO mice develop fatty liver, which is a well-known driver for HCC." (PMID 38332150, 2024). "However, the effect of SIRT6 on regulating the NLRP3 inflammasome in hepatic steatosis progression remains elusive." (PMID 36558977, 2022). "Liver-specific silencing of SIRT6 leads to hepatic steatosis and inflammation." (PMID 35256601, 2022). "Altogether, our results indicated that the improvement of MetS and hepatic steatosis by LWE could be attributed to the activation of the SIRT6/SREBP1 /FAS/DGAT1 pathway to reduce lipogenesis." (PMID 35681388, 2022). "Studies have demonstrated that SIRT6 could prevent fatty liver disease by reducing oxidative stress, endothelial dysfunction, and fibrosis." (PMID 35681388, 2022). "Hepatic-specific ablation of Sirt6 increased liver steatosis." (PMID 29535637, 2018). "Sirt1 and Sirt6 also both show protective effects against hepatic steatosis." (PMID 21373642, 2011). "Considering the previous observations as well as our findings, it can be speculated that both Sirt1 and Sirt6 are involved in the RGZ-mediated amelioration of hepatic steatosis." (PMID 21373642, 2011). "Considering the previous findings implicating AMPK in TZD's beneficial effects, and the potential interdependence of AMPK and sirtuins, we speculated that TZD may protect against hepatic steatosis by activating the Sirt6-AMPK pathway." (PMID 21373642, 2011). "Interestingly, we found that the RGZ-mediated beneficial effect against hepatic steatosis is dependent on the Sirt6-AMPK pathway." (PMID 21373642, 2011). "The phosphorylation levels of AMPK at Thr172 and LKB1 at Ser428 were significantly increased by RGZ treatment, suggesting that the Sirt6-AMPK pathway may be involved in the beneficial effects of RGZ on hepatic steatosis." (PMID 21373642, 2011). "To determine whether Sirt6 is causally related to the development of hepatic steatosis and its amelioration by RGZ, we directly inhibited Sirt6 by RNAi-mediated gene silencing in AML12 mouse hepatocytes." (PMID 21373642, 2011). "Similar aggravation of hepatic steatosis was also observed in liver-specific Sirt6 knockout mice." (PMID 21373642, 2011). "We propose Sirt6 as a possible therapeutic target for hepatic steatosis." (PMID 21373642, 2011). "In this study, we aimed to elucidate whether Sirt6 is involved in RGZ-mediated protection against hepatic steatosis." (PMID 21373642, 2011). "This study was designed to test whether Sirt6 contributes to the protective effects of the TZD rosiglitazone (RGZ) on hepatic steatosis." (PMID 21373642, 2011). "In light of previous findings, our data demonstrating the involvement of Sirt6 in the RGZ-mediated protection of hepatic steatosis suggest that Sirt6 may have functional similarities with Sirt1 as a metabolic regulator." (PMID 21373642, 2011). "In addition to the regulatory effects of Sirt1 and Sirt6 on diabetes and hepatic steatosis, other sirtuins including Sirt2 and Sirt3 also demonstrate the possibility of acting as metabolic regulators, which suggests that sirtuins’ actions on metabolism seem to be, in part, overlapping and redundant." (PMID 25133775, 2014).
Hepatic steatosis (continued). "On a chow diet, nearly half of the Sirt6 LKO mice develop fatty liver at 5–6 months of age, and 90% of LKO mice have fatty liver by 13 months of age." (PMID 36831330, 2023). "The overexpression of deacetylated ACSL5 mutant (K98R/K361R/K367R) in the liver of Sirt6 LKO mice significantly improves high-fat diet-induced glucose intolerance and fatty liver." (PMID 36831330, 2023). "Sirt6 knockdown increased hepatocyte lipid accumulation and abolished the effect of RGZ on hepatic steatosis." (PMID 29535637, 2018). "In vitro experiments, confirmed the function of Sirt6 by using the free fatty acid stimulated mouse hepatocyte cell line, AML 12, which also showed the protection from hepatic steatosis following rosiglitazone treatment." (PMID 22966224, 2012). "To address the role of Sirt6 in the beneficial effects of RGZ, we first determined the metabolic effects of RGZ on hepatic steatosis." (PMID 21373642, 2011). "SIRT6-deacetylated X-box binding protein 1 (XBP1) is transactivated in Lys257 and Lys297, and promotes the degradation of XBP1s protein through the ubiquitin-proteasome system, thereby reducing endoplasmic reticulum stress and liver steatosis." (PMID 36008973, 2022). "To test whether SIRT6 mediates the effects of NAMPT on ethanol-induced liver steatosis, we also used adenovirus to overexpress NAMPT-HA in the livers of Sirt6-HepKO mice fed with ethanol." (PMID 30794635, 2019). "Like other Sirt1 activators, RGZ administration increased Sirt6 expression and phosphorylation levels of LKB1 and AMPK, and provided protection from hepatic steatosis, suggesting that RGZ may act as a Sirt6 activator and a therapeutic strategy for NAFLD." (PMID 21373642, 2011). "This inhibition leads to downregulation of mRNA levels of SIRT6 target genes ACC1, SCD1, FAS, and CRFVL6, and reduced serum inflammatory factors TNF-α, IL-1β, IL-4, IL-6, IL-2, and chemokine MCP-1, which in turn attenuates hepatic steatosis and inflammation in HFD mice." (PMID 40292292, 2025). "Therefore, increasing the expression of SIRT6 and suppressing the expression of SREBP-1/FAS/DGAT1 may be part of the mechanism of LWE-alleviated MetS and hepatic steatosis in Lepr−/− rats." (PMID 35681388, 2022). "The absence of SIRT6 increases the expression of genes responsible for hepatic long-chain fatty acid uptake and reduced expression of genes for β-oxidation leading to accumulation of triglycerides and fatty liver disease and hepatic steatosis." (PMID 30671172, 2018). "SIRT6 KO, and especially hepatic SIRT6 KO, abolished these effects of ATL and failed to attenuate hepatic steatosis in mice." (PMID 36558977, 2022). "A previous study showed that SIRT6 interacted with spectrin beta chain, non-erythrocytic 1 (SPTBN1) to crosstalk with TGF-β signaling, and contributed to fatty liver disease." (PMID 36558977, 2022). "NAMPT overexpression reduced hepatic TG levels in ethanol-fed control mice but not in Sirt6-HepKO mice, indicating SIRT6 is also required for NAMPT’s effects on alleviating hepatic steatosis." (PMID 30794635, 2019). "NASH mice have significantly lower levels of SIRT6 in their livers than normal mice, and the absence of SIRT6 in the liver accelerates hepatic steatosis, IR, and inflammation as well as exacerbates NASH-induced hepatic injury, whereas SIRT6 transgenic mice are unaffected by diet-induced NASH." (PMID 40292292, 2025).